IL18 (interleukin 18)
Diseases named in the same sentence as IL18 in open-access papers (continued):
Sharing a sentence is not in itself a finding about the gene and the disease.
tumor (continued). "Their experiments revealed that T cells harbouring inducible IL-12 had limited anti-tumour effects and severe toxicity in vivo, whereas T cells expressing IL-18 resulted in enhanced anti-tumour responses without toxicity." (PMID 32183246, 2020). "A strong NK-cell activity and tumor specific cytotoxic T lymphocyte (CTL) response against Lewis lung carcinoma (LLC), with significant tumor regression, have also been observed on simultaneous administration of Apoptin and Interleukin-18." (PMID 32671070, 2020). "A second immunotherapy approach consists of tumor extirpation to infiltrate it later with Th1 cells and IL-15, IL-18, and IFN-α cytokines and subsequently reimplant the tumor-tissue into the patient, in a subcutaneous region closer to some lymph nodes intraperitoneal." (PMID 33276556, 2020). "Intriguingly, stimulation with IL-12 and IL-18 without TCR stimulus induces a comparable degree of anti-tumor activity in γδ T cells to TCR crosslinking by killing tumor cells and driving cancer cells into senescence." (PMID 31947966, 2020). "IL-18 inhibition, and the combination of both IL-1β and IL-18 inhibition also had no impact on tumor cell growth." (PMID 33042810, 2020). "Indeed, adoptive transfer of iNKT cells activated in vitro with a combination of IL-12 and IL-18 robustly produces IL-2 and IFN-γ, which in turn activates NK cells to mediate anti-tumor response in vivo." (PMID 32708464, 2020). "Efficient tumor-lytic activity after pharmacologic Vδ2 TCR-stimulation correlates with granzyme B and IFN-γ/TNF-α production in γδ T cells, parameters which we and others found to be enhanced when IL-2, IL-12, and IL-18 are added." (PMID 31947966, 2020). "As with TNF-α and IL-1β, IL-18 may also exhibit both pro- and anti-tumour activity in CRC, depending on the stage of progression and immune effector cells responsive to IL-18." (PMID 32168834, 2020). "The loss of epithelial and stromal IL-18 but not NLRP6, was associated to lower tumor immune infiltrates in the lymphoid compartment and higher Programmed cell Death receptor 1 (PD-1) expression." (PMID 33255437, 2020). "In this study, we evaluated the expression of CCL2, IL18, TNF-α, and IL23α, and whether they play a role in tumor progression or suppression." (PMID 32695310, 2019). "Also, the activation of Tumor Necrosis Factor (TNF) family ligands that expressed on the surface of NK cells with IL-2, IL-15, IL-12, IL-18, and CD40 cytokines production induce NK cell cytotoxicity against tumor target cells and IFNγ production." (PMID 31457012, 2019). "Collectively, these data indicate that higher IL18 expression is significantly involved in the infiltration of CD8+ T cells, NK cells, and γδ T cells in SKCM, resulting in a higher survival rate via the anti-tumor activities of the effector cells." (PMID 31731729, 2019). "Other armored CARs in development include an IL-18-secreting CD19 or MUC16 CAR, which appears to modulate the tumor microenvironment of both hematologic malignancies and solid tumors and helps enhance endogenous anti-tumor T cell responses." (PMID 30915277, 2019). "To understand which molecules were responsible for this activity we performed experiments of THP1 activation with tumor cell supernatants in the presence of neutralizing Abs and BoxA to inhibit IL-1α, TNF-α, IL-18 and HMGB1, respectively, which are released by tumor cells." (PMID 30760333, 2019). "Tumor regression in response to combination treatments correlated strongly with elevated tumor expression of CD8b, Ifng, Tnfa, Ccl5 and Il18 in the non-injected tumors." (PMID 31921384, 2019). "In addition, interactions between IL18, which is an immunity-enhancing cytokine, and IL18BP at the cell surface result in anti-tumor effects, including stimulation of T cell proliferation and increases in natural killer cell activity." (PMID 31257224, 2019).
tumor (continued). "Consistent with our in vitro experiments, analysis of NeuT tumor protein lysates showed that anti-MMP-9 treatment increases expression of CXCL10 and other T cell–stimulating factors, such as interleukin (IL)-12p70 and IL-18." (PMID 30500835, 2018). "In ID8hPON2 cells, the expression profile of many genes known to regulate tumor growth including BRCA1, cyclin and cyclin-dependent kinase 20, PTK2, Hypoxia-upregulated protein 1, p21-activated kinase 3, IL-18, IL-33, IGF-1, IGFBP2 and RNA-binding protein 9, were identified." (PMID 29531225, 2018). "Interestingly, we found that the serum levels of IL-18 and IFN-γ in xenograft tumor model mice after LPS stimulation were significantly increased compared with sham mice and allograft model mice." (PMID 29690614, 2018). "In the absence of Th1-like cytokines, IL-18 not only accelerates tumor progression but also promote PD-1 express on mature NK cells." (PMID 29921237, 2018). "The cytokine profile identified in the ACP RNA-Seq dataset, in particular the significantly higher expression of IL1A (18.1-fold), IL18 (14.8-fold), TNF (10.4-fold) and IL1B (7-fold) in human ACP tumours relative to controls, was suggestive of inflammasome activation [Suppl." (PMID 29541918, 2018). "IL-12/IL-15/IL-18 has previously been reported to promote the activation of NK cells in the absence of tumor stimulation." (PMID 30400618, 2018). "As a result, we assumed that tumor derived IL-18 did not affect the activities of NK cells themselves, although IL-18 increased the overall proportion of immunosuppressive NK cells." (PMID 28415798, 2017). "Minimal expression of 107a and IFN-γ was detected in CD56dimCD16dim/− NK cells subsets, and this expression was not changed by blocking tumor-derived IL-18." (PMID 28415798, 2017). "Together, these results indicate that caspase-1-mediated non-IL-1/IL-18 pathway(s) is likely to drive PsV-induced tumour regression." (PMID 28397782, 2017). "Serum IL-18 levels remained as an important prognostic factor for both RFS and OS even after adjustment for other prognostic clinical variables, such as hormone receptor status, HER2 overexpression, tumor size, and nodal status." (PMID 28415798, 2017). "However, several studies have shown that EBV infection can induce the NLRP3 inflammasome to produce IL-1β and IL-18, leading to the growth and activation of anti-apoptosis mechanisms of EBV-infected tumor cells." (PMID 28732079, 2017). "IL-18, another effector molecule of NLRP3 inflammasome, could inhibit the growth of NK cells to promote tumor growth and metastasis by inducing the expression of PD-1." (PMID 29312552, 2017). "The adoptive transfer of murine splenic NK cells pretreated with IL-12, IL-15, and IL-18, but not naïve or IL-15- or IL-2-pretreated NK cells, into tumor-bearing mice effectively reduced tumor growth, than that of when combined with radiation therapy." (PMID 28955346, 2017). "We determined whether abrogation of IL-18 signaling during DNA vaccine plus α-GalCer and MPL immunization only would lead to reduced therapeutic effect against TC-1 tumor." (PMID 26811064, 2016). "To do this we administered anti-mouse IL-18 mAb, or isotype control mAb, to C57BL/6 mice during vaccination, one day prior to all of the vaccinations, for 3 weeks and the tumor volume was monitored up to 6 weeks after the tumor challenge." (PMID 26811064, 2016). "We found that blockade of IL-18 signaling in E7 DNA vaccine plus α-GalCer and MPL combination mice reduced E7-specific IFN-γ, and that this treatment decreased the protection against tumor growth compared with isotype control mAb." (PMID 26811064, 2016). "In addition, several inflammatory cytokines, including TNF-α, IL-1, IL-6, TGF-β and IL-18, have been documented to increase HIF-1α expression or transcriptional activation in tumor cells." (PMID 26910835, 2016).
tumor (continued). "IL-1β, IL-18, IL-6, IL-8 and TNF-α are produced by macrophages through the activation of toll-like receptor signaling, and their production is involved in the clearance of tumor cells by macrophages." (PMID 27671753, 2016). "The hUMSCs/IL-18 did not migrate to the lower chamber when the tumor cells were not present, but they were stimulated to migrate by the addition of tumor cells into the lower chamber." (PMID 25780408, 2015). "The tumor inhibition and tumor protection effects of GM-CSF were then investigated with or without IL-18." (PMID 26186692, 2015). "In this study, the co-expression of membrane-bound GM-CSF and IL-18 enhanced anti-tumor immunity without the potential risks of systemic toxicity of soluble cytokines." (PMID 26186692, 2015). "In contrast, CT26/IL-18 revealed no tumor protection effects and showed a similar degree of tumor inhibition to PBS control." (PMID 26186692, 2015). "In the present study, we evaluated whether gene therapy with both IL-18 and HSV-TK is more effective than gene therapy with IL-18 or HSV-TK alone for the induction of specific anti-tumor immunity to treat distant tumors and suppress primary tumor growth." (PMID 25051201, 2014). "The IL-18 and TK/GCV dual gene therapy system may have synergistic efficacy by increasing the sensitivity of target cells as well as the tumor-specific CTL activity and the accumulation of immune cells." (PMID 25051201, 2014). "In addition, recombinant IL-18 inhibited tumor progression in the AOM/DSS-induced CAC, suggesting a protective role for IL-18 from inflammation-promoted tumorigenesis in the colon." (PMID 24474192, 2014). "IL-18 was recently shown to prime NK cells to have unique helper activity, and the resulting “helper” cells promote activation of DC and DC-mediated recruitment of effector CD8+ T cells to the tumor microenvironment." (PMID 24376549, 2013). "In these models, it has been shown that the absence of inflammasome-related interleukins, mainly IL-18, can greatly impact carcinogenesis and tumor progression." (PMID 23606794, 2013). "In experimental cancer models, IL-18 expression in tumor cells has been shown to enhance both specific and non-specific anti-tumor immune responses." (PMID 23847622, 2013). "In our model, abrogation of tumor-induced hepatic IL-18 did not involve any decrease of IFN-gamma level, which also significantly increased in the hepatic blood of same animals (data not shown)." (PMID 21569399, 2011). "Furthermore, 13.9% of the tumor in the Ctrl group contained between 11 and 50 CD4+ cells per microscopic field compared to 4.3%, 6.2% and 1.8% respectively for the mice in which IL-18, IFN-γ, or both were neutralized." (PMID 21935389, 2011). "Therefore, by acting on host and tumor-dependent responses to IL-18, RVL very efficiently inhibited cancer cell arrest and growth initiation in the tumor microenvironment." (PMID 21569399, 2011). "In all our experiments, regardless of the site of injection of the tumor cells or method of delivery, IL-18 reduced the tumor burden significantly." (PMID 21935389, 2011). "The central role of the immune system, particularly effector T cells, in expanding the efficacy of time-dependent chemotherapy was confirmed by the abrogation of the IL-18 and topotecan interaction in tumor-bearing SCID mice lacking T cells." (PMID 21609494, 2011). "Such inhibition may contribute to the anti-tumor effect of LCA by attenuating the processing and secretion of the cytokines interleukin-1β and interleukin-18, thereby preventing growth and proliferation of neighbouring NB cells in culture." (PMID 21992775, 2011). "IL-18 also induced an increase in tumor infiltration of macrophages and neutrophils but not NK cells." (PMID 21935389, 2011).
tumor (continued). "Among these, manipulation of BCG to secrete Th1 cytokines (e.g., IL-2, IL-18, IFN-γ, and IFN-α), alone or in combination with coexpression of bacterial or tumor antigens, represents one of the most attractive strategies for the development of improved vaccines." (PMID 21941579, 2011). "In contrast to our data, IL-18 treatment did not change tumor infiltration of CD4+ T cells or macrophages, and reduced the number of CD8+ T cells." (PMID 21935389, 2011). "Intratumoral injection of IL-18 resulted in significant infiltration of macrophages but not T cells within the tumor mass." (PMID 21935389, 2011). "In C57BL/6 mice, combination therapy decreased tumor growth relative to control mice (p < 0.05), while IL-18 or topotecan alone did not have any significant effect." (PMID 21609494, 2011). "Given that the combination of IL-2+ IL-12+ IL-18 failed to enhance IL-17 production, alternative strategies will be required to promote this effector pathway within the tumor environment." (PMID 21203522, 2010). "Median survival was similar in mice receiving Doxil therapy with or without IL-18; however tumor cures were only observed in mice receiving combinatorial therapy." (PMID 20003308, 2009). "Thus, by inhibiting Tregs and promoting conventional T cells, human IL-18 may have potential to restore immunocompetence in cancer patients, and thereby augment the effects of cytotoxic and biologic therapies, in order to provoke and maintain an effective anti-tumor immune response." (PMID 18818761, 2008). "Flow cytometry revealed that IFN‐γ is the predominant cytokine produced by NK cells upon IL‐12, IL‐15 and IL‐18 stimulation, and that AREG‐KO NK cell–CM induced more cell death than WT NK cell–CM, indicating that NK cell–derived AREG protects against IFN‐γ–mediated tumor cell apoptosis." (PMID 41082397, 2026). "However, given the reported context-dependent effects of IL-18 in GVHD, along with its emerging promise in immunotherapy, careful examination of its abrogation will be required to balance its proreparative and graft-versus-tumor effects." (PMID 40935830, 2025). "Additionally, IL-18 signaling pathway and TNF pathway clarifying further their anti-tumor role." (PMID 39232806, 2024). "This analysis identified a number of potential associations that differed depending on the NK state, including a number of immunostimulatory interactions (Ifng, Ccl5, Il18) involving newly recruited NK cells, but not those that had been retained within the tumor for several days." (PMID 38267402, 2024). "Measurement of tumor volume after 30 days showed that compared to the control group, the subcutaneous tumor volume significantly decreased in the MLT group, si-NLRP3 group, and IL-1β Ab group, while it significantly increased in the oe-NLRP3 group and IL-18 Ab group." (PMID 39230586, 2024). "In addition to targeting inhibitory cytokines in TIME, CAR-T cells could be equipped with ability to secrete pro-inflammatory cytokines such as IL-12 and IL18 to remodel suppressive TIME and boost anti-tumor effects." (PMID 38918817, 2024). "CyTOF analysis demonstrated that IL-18-secreting CAR-T cells could induce the expansion of NK cells, DCs, and endogenous CD8 + T cells and regulate endogenous immune cells phenotype, thereby reversing immunosuppressive TIME and amplifying anti-tumor response." (PMID 38918817, 2024). "Notably, TRIM31 (logFC = 1.14), ANXA1 (logFC = 1.05), GBP1 (logFC = 1.01), BIRC3 (logFC = 0.99), APOL1 (logFC = 0.97), IL18 (logFC = 0.94), ANXA2 (logFC = 0.89), BHLHE40 (logFC = 0.83), and EPHA2 (logFC = 0.75) exhibited significant upregulation in tumour tissues." (PMID 38254861, 2024). "Besides, lower IL18 expression was also related to lower scores of processing machinery, CD8 T effector, antigen cytolytic activity, and MHC-HLA, which indicates the infiltration of lower immune cells in the tumor microenvironment." (PMID 36707882, 2023).
tumor (continued). "Indeed, IL-18 release is dependent on NLRP3 activation, and its signaling through the IL-18R receptor induces the exhaustion of CD8+ T cells and limited migration into the tumor." (PMID 37298187, 2023). "During tumor progression, MCs accumulate near blood vessels located around the tumor, secreting several mediators promoting angiogenesis and suppressing the immune response, including vascular endothelial growth factor (VEGF), histamine, tumor necrosis factors (TNF-α), and interleukin 18 (IL-18)." (PMID 36835050, 2023). "Interestingly, in murine invasive breast cancer models, the absence of a functional NLRP3 inhibited tumor growth, and NK cell depletion abolished the anti-tumoral effect independently of IL-1 β and IL-18 effector mechanisms." (PMID 37715239, 2023). "Interestingly, we found that Il22ra2 expression in tumor-infiltrating cells was suppressed by PGE2 through the suppression of the expression of RA-synthase genes and may also through the induction of IL-18, an inhibitor of Il22ra induction." (PMID 36932082, 2023). "Given that IL-18 is known to induce anti-tumor immunity, but based upon these data may also concomitantly increase A2AR expression, we hypothesized that suppression mediated by A2AR signaling may limit the overall therapeutic effect of IL-18." (PMID 37914685, 2023). "Compared with that in tumours, the increase of IL-1β, IL-18, and HMGB1 levels in the serum was not severe, suggesting that TIOs+NIR3-triggered antitumour immune response is relatively safe and does not cause hyperactive immune response or substantial systematic inflammation." (PMID 37673934, 2023). "Furthermore, we found that IL18 promoter methylation was significantly related to the down-regulation of immune checkpoint molecules and increase of CD8 + T cell infiltration in RCC tumor tissues." (PMID 36707882, 2023). "Notably, chemotherapy without CD47 blocking strategy enhances CD47 expression on tumor cells via inducing IL-18 release from macrophages, which increases L-amino acid transporter 2 (LAT2) in tumor cells." (PMID 37380989, 2023). "And recombinant IL-18 did not rescue tumor burden and CD8+ T cells inactivation in IL-37tg mice." (PMID 35046386, 2022). "To determine whether circulatory levels of IL9 or IL18 in PDA patients differ from healthy individuals and whether they potentially reflect systemic tumor responses, we compared IL9 and IL18 blood levels of our patient cohort with an age-matched control group of healthy individuals (n=30)." (PMID 36131941, 2022). "In addition, studies of IL-1β, IL-11, IL-17, IL-18, and TNF also indicate that proinflammatory cytokines are key regulators for TME in inhibiting tumor cell proliferation, reducing inflammation, and preventing tumor metastasis." (PMID 35069767, 2022). "Like IL18, co-expressed IL36γ acts in an autocrine fashion to augment expansion and persistence of CAR T cells, and also acts in a paracrine fashion promoting the maturation of antigen presenting cells and supporting tumor recognition by host T cells through antigen spreading." (PMID 36700225, 2022). "Cisplatin, but not ifosfamide or methotrexate, could also increase the content of IL-18 in macrophage-conditioned media and tumors, and the effects of these drugs on CD47 upregulation in tumor cells observed in vitro and in vivo were correlated with IL-18 levels induced by them." (PMID 36274066, 2022). "This may suggest that activated caspase-1 is associated with the initiation of inflammatory programmed cell death (pyroptosis) and, in turn, inhibits tumor growth rather than upregulating pro-inflammatory molecules such as IL-1β and IL-18." (PMID 35883451, 2022). "Interestingly, despite the higher proportion of TMEM/TEFF than TVM cells in spleen and tumor-draining lymph nodes after IL-12+IL-18 expression, this is not what is observed on CD8+CD44hi T cells infiltrating the tumors." (PMID 36330506, 2022).